TLR4 (toll like receptor 4)
Diseases named in the same sentence as TLR4 in open-access papers (continued):
Sharing a sentence is not in itself a finding about the gene and the disease.
lupus (continued). "Our study also demonstrated that TLR4 was significantly higher in the DCs of lupus-prone NZB/WF1 mice compared with C57BL/6 mice." (PMID 27545083, 2016). "Inhibition of TLR4, on the other hand, reduces autoantibody production and decreases glomerular IgG deposits in the kidney for some lupus-prone murine models." (PMID 26648937, 2015). "This suggests that TLR4 hyperresponsiveness to gut flora (which contains LPS) plays an essential role in lupus development." (PMID 26648937, 2015). "Ameliorated autoantibody production and glomerulonephritis are found in TLR4−/− pristane-induced lupus model and lupus-prone TLR4−/− B6." (PMID 26068236, 2015). "Previous work has shown that endotoxin, now known to be a TLR4 agonist, can exacerbate disease in a variety of strains of lupus-prone mice." (PMID 24086313, 2013). "We therefore decided to examine if the findings suggesting a role for TLR2 and TLR4 in the milder lupus models would be confirmed in MRLlpr mice." (PMID 24086313, 2013). "In addition, blocking spleen tyrosine kinases (the shared downstream signaling molecules of Fc gamma receptor (FcγR) and TLR-4) can alleviate lupus-induced inflammation." (PMID 38022571, 2023). "Notably, pharmacological inhibition of the activity of ACK1 not only alleviated the conditions of TLR4-mediated endotoxic shock mice but also relieved the conditions of TLR7-mediated lupus model mice." (PMID 35669783, 2022). "Blockade of TLR4 significantly decreased serum autoantibody levels and attenuated renal damage in lupus mice, suggesting that TLR4 might be a potential target for prohibiting plasma cell responses and treating SLE." (PMID 36220996, 2022). "In vivo studies showed that the inhibition of ACK1 activity by AIM-100 could significantly protect mice from the TLR4 agonist lipopolysaccharide (LPS)-mediated endotoxin shock and alleviate the condition of imiquimod-mediated lupus-prone mice and MRL/lpr mice." (PMID 35669783, 2022). "In addition, an increase in TLR4 cutaneous expression was also observed in human pemphigus and systemic lupus erythematosus." (PMID 33917661, 2021). "Moreover, in TLR2- and TLR4-deficient C57BL/6lpr/lpr, as well as pristane-injected TLR4-deficient animals, development of murine lupus, was mitigated, while TLR2 and TLR4 activation enhanced disease." (PMID 31266174, 2019). "In addition, the stimulation of toll-like receptor 4 agonist accelerates lupus symptoms of BXSB mice, resulting in a decreased activation threshold of B cells." (PMID 29849184, 2018). "Third, the elevation of TLR4 can induce lupus-like autoimmune disease." (PMID 28769820, 2017). "Importantly, knocking out ERα in both lupus-prone and control mice resulted in impaired TLR4 activation in immune cells, indicating that estrogen and ER signaling can influence TLR4 responsiveness." (PMID 26648937, 2015). "Lupus spontaneously develops in mice with overexpression of a molecular chaperone of TLR4 that increases its responsiveness; but when commensal bacterial flora was deleted through treatment with antibiotics, the enhanced lupus phenotype was largely ameliorated." (PMID 26648937, 2015). "Activation of TLR4 also promotes lupus disease activity in transgenic mice." (PMID 26648937, 2015). "Wang also demonstrated that PA alleviates depressive-like symptoms in systemic lupus erythematosus (SLE)-induced MRL/lpr mice by suppressing HMGB1/TLR4/NF-κB signaling." (PMID 41535967, 2026). "Mice overexpressed with TLR4 were shown to generate the SLE-like autoimmunity, while upregulated TLR4 levels were found in pulmonary and splenic tissues from pristane-induced lupus mice in this study." (PMID 37700342, 2023). "Furthermore, our preliminary results showed that QB could ameliorate renal lesions in lupus MRL/lpr mice by inhibiting the expression of TLR4." (PMID 35571092, 2022).
lupus (continued). "Furthermore, serum BG also enhances the impact of LPS upon lupus progression because BG administration alone could enhance lupus and the synergistic effect of BG upon LPS through TLR-4 and Dectin-1 are reported." (PMID 31964918, 2020). "Interestingly, kringle-2 was found to be the locale of autoantibodies in the antiphospholipid syndrome in patients with Systemic Lupus Erythematosus and was also found to act as a potential neuroinflammatory factor that stimulates microglial toll-like receptor 4 (TLR4)." (PMID 30333979, 2018). "Similarly, overexpression of TLR4 in mice has led to the production of anti-dsDNA and the immune complex-mediated glomerulonephritis, suggesting that TLR4 signaling plays critical roles in lupus progression." (PMID 24324506, 2013). "Therefore we cannot be sure that combined deficiency of TLR2 and TLR4 would not have resulted in protection from lupus in MRLlpr mice where none was seen with deficiency in just one receptor." (PMID 24086313, 2013). "In contrast, the expression of TLR4 in systemic sclerosis (SSc) and systemic lupus erythematosus (SLE) is lower than it is in RA." (PMID 20419126, 2010). "Our study suggests that Nrf2 gene overexpression (Blood PCs 0.28%, Blood PC 0.92%; Kidney PCs 5.75%, Kidney PC 2.06%) regulates TLR4+CXCR4+ PCs and PC levels in the blood and kidneys of a mouse model of lupus, with concomitant amelioration of damaged tissue." (PMID 37872565, 2023). "In the lupus-prone model, TLR2 or TLR4 knockdown downregulated the antinuclear antibody levels and alleviated disease symptoms." (PMID 37667233, 2023). "In systemic lupus erythematosus (SLE), downregulation of miR-4512 leads to high expression of TLR4 and CXCL2 in macrophages, which release more pro-inflammatory factors." (PMID 35634335, 2022). "TLR4 engagement on mouse FDCs induces up-regulation of Fc receptors and integrins, while TLR7 on FDCs promotes auto-reactive B cells in a mouse model of systemic lupus erythematosus through secretion of IFN-α." (PMID 34424268, 2021). "Previously, we have shown that hAAT treatment inhibited BMDC activation and cytokine secretion upon stimulation with TLR4 or TLR9 agonists in B6 and lupus-prone B6." (PMID 31470606, 2019). "In the study of systemic lupus erythematosus (SLE), activation of TLR4 has been shown to promote autoreactive plasma cell responses and enhance autoantibody production." (PMID 30906792, 2019). "Although previous findings in plasma cells from the bone marrow showed the absence of TLR expression, we and others recently identified a novel subset of autoreactive long-lived plasma cells with surface TLR4 and CXCR4 expression in human and murine lupus." (PMID 31795353, 2019). "Decreased anti-dsDNA antibodies were observed in TLR2 and TLR4 knockout C57BL/6 (lpr/lpr) mice; and autoantibodies were induced by LPS stimulation through the TLR4-dependent cell signaling pathway in lupus-prone mice." (PMID 30150778, 2018). "The importance of interferons was highlighted in our previous results on the TLR4 signaling pathway, where TLR4, TICAM1, TICAM2, TBK1, IRF3, IFNA1, and IFNA2 mRNAs showed changes in the murine lupus-like models." (PMID 29349090, 2017). "The impact of TLR4 inactivation has been investigated in C57BL/6lpr/lpr mice and lupus severity was markedly reduced." (PMID 24252506, 2013). "The interaction of TLR4 and inflammatory cytokines may lead to pulmonary fibrosis in AAV and lupus patients." (PMID 38022571, 2023). "In patients with systemic lupus erythematosus and concurrent active nephritis, the level of TLR2 in peripheral blood T cells and of TLR4 in B cells and monocytes was increased, and the rate of protein excretion in the urine was associated with TLR expression in these cells." (PMID 32079183, 2020). "Ligand to TLR4 or a mixture of ligands to TLR7 and TLR9 were used, based on our prior experience demonstrating additive effect of TLR7 and 9 ligands in unmasking reversible anergy in NZB lupus." (PMID 31632407, 2019).
lupus (continued). "Also, HMGB1, a DNA-binding protein, and lupus autoantigen, released under inflammatory conditions can induce NF-κB activation in a TLR2 and TLR4-RAGE-dependent manner in mononuclear phagocytes and neutrophils as well as in mesangial cells." (PMID 29650017, 2018). "However, like the deficiency of TLR4, in MRL/lpr mice, TLR2 deficiency did not affect lupus pathogenesis, possibly due to mouse strain differences." (PMID 26648937, 2015). "Recent work has suggested that TLR2 and TLR4 may also play a role in murine lupus in the absence of exogenous ligand administration." (PMID 24086313, 2013). "Exosomes derived from lymphocytic leukemia (CLL) can target TLR7 signaling to promote innate immunity, while exosomes isolated from systemic lupus erythematosus (SLE) patients' serum can produce abundant IFN-α, TNF-α, IL-1β, and IL-6 via the TLR1/2, TLR7, TLR9, and TLR4 pathways." (PMID 32565722, 2020). "Notably, ablation of IRF4 in DKO DCs was effective in ameliorating TLR4- but not TLR9-mediated hyper-responsiveness indicating that DC dysfunction in this lupus model may encompass both IRF4-dependent and IRF4-independent pathways." (PMID 26544714, 2015).
endothelial dysfunction (84 papers, 2010 to 2026). In vascular diseases, endothelial dysfunction is a systemic pathological state of the endothelium (the inner lining of blood vessels) and can be broadly defined as an imbalance between vasodilating and vasoconstricting substances produced by (or acting on) the endothelium. "In fact, it causes endothelial dysfunction and activates TLR4 and the TLR4/NFκB axis in CMs with often unhealthy consequences." (PMID 37112659, 2023). "DENV nonstructural protein 1 (NS1) directly activates Toll-like receptor 4 (TLR4)-expressing immune cells to trigger the secretion of proinflammatory cytokines that cause endothelial dysfunction and thrombocytopenia." (PMID 35045094, 2022). "TLR4 has also been implicated in the development and progression of cardiovascular disease by inducing endothelial dysfunction." (PMID 31316302, 2019). "We previously showed that the mechanism by which palmitate causes endothelial dysfunction involves TLR4-mediated induction of the inflammatory NF-κB pathway in endothelial cells." (PMID 22479476, 2012). "Our observations suggest that loss of TLR4 increases superoxide generation which reduces the biological activity of endothelial derived nitric oxide and thereby explains the endothelial dysfunction and associated cardiovascular phenotype in TLR4−/− mice." (PMID 21513697, 2011). "Additionally, we confirmed the involvement of Gal-3 in A-ED, causing endothelial dysfunction, inflammation, and fibrosis in the penile corpus cavernosum through the TLR4/MyD88/NF-κB pathway." (PMID 38378809, 2024). "Similarly, dengue nonstructural protein (NS1) shed during acute infection acts as a viral pathogen-associated molecular pattern that activates TLR4 on leukocytes and endothelial cells leading to inflammation and endothelial dysfunction." (PMID 37200377, 2023). "Since endothelial dysfunction and TLR4 activation causes metabolic dysfunctions, we tested our hypothesis FN-EDA contributes to the development of IR via TLR4." (PMID 32499562, 2020). "Therefore, we next set out to determine whether TLR4 signaling contributes to mediating TBI-associated endothelial dysfunction by performing in vivo treatment with TAK-242, a specific inhibitor of TLR4." (PMID 30704505, 2019). "LBP indirectly enhances the activation of ‘Toll Like Receptor 4′ signalling, which is crucial in CKD-associated inflammatory response and leads to endothelial dysfunction and chronic inflammation." (PMID 41325840, 2025). "Studies have demonstrated that LPS can induce vascular oxidative stress by activating Toll-like receptor 4 (TLR4), resulting in endothelial dysfunction and vascular inflammation." (PMID 38613099, 2024). "Fiber interventions, especially RS, reduced endotoxemia, vascular TLR4 expression, and improved endothelial dysfunction." (PMID 37615336, 2023). "Preterm infants with NEC also have been shown to have increased levels of TLR4 with reduced nitric oxide synthase (eNOS) expression, suggesting that intestinal endothelial dysfunction by endothelial TLR4 activation contributes to the development of NEC." (PMID 37082706, 2023). "In our study, Ang II triggered the inflammatory injury, enhanced transcytosis and eNOS/iNOS imbalance-induced endothelial dysfunction in ECs through activating the TLR4 signalling pathway and then led to BBB disruption." (PMID 36369944, 2022). "Inflammatory injury, enhanced transcytosis, and endothelial dysfunction are the changes in brain ECs due to Ang II-induced TLR4 activation." (PMID 36369944, 2022). "Bomfim and colleagues described that the inhibition of TLR4 activation by chronic treatment with anti-TLR4 antibody reduced both BP and endothelial dysfunction in spontaneously hypertensive rats." (PMID 33413552, 2021). "An experimental study has shown that the western diet provokes TLR4-induced endothelial dysfunction and suggesting a potential role of TLR4-related inflammation in increasing the risk of AIS." (PMID 32264928, 2020).
endothelial dysfunction (continued). "In endothelial cells, activation of TLR-4 promotes elevated reactive oxidative stress, reduces eNOS coupling leading to a reduced NO-production and bioavailability leading to endothelial dysfunction." (PMID 25826421, 2015). "Altogether, these results allow us to propose that the anti-TLR4 antibody treatment improves endothelial dysfunction in SHRs, and this improvement most likely occurs by increasing NO bioavailability." (PMID 25093580, 2014). "One of the mechanisms that explain the endothelial dysfunction induced by TLR4 activation is the reduction of NO contribution to vascular responses." (PMID 25093580, 2014). "Further study is needed to better understand the potential role of TLR4 on endothelial dysfunction in this and other patient populations." (PMID 24918924, 2014). "Our in vitro findings complement the current understanding of the role of TLR4 signaling in the pathogenesis of endothelial dysfunction proposed by Liang and colleagues." (PMID 24918924, 2014). "In contrast, a dysbiotic microbiome enriched in Gram‐negative bacteria can release lipopolysaccharide (LPS) into circulation when intestinal permeability is impaired, activating the TLR4/NF‐κB pathway and promoting systemic inflammation and endothelial dysfunction." (PMID 41501330, 2026). "Concurrently, activation of innate immune pathways, particularly the TLR4/NF-κB axis, induces pro-inflammatory cytokine release and endothelial dysfunction, while complement activation and adaptive immune responses contribute to chronic inflammation and fibrosis." (PMID 41827876, 2026). "Also, the mediator NPY suppresses p38/NF-κB in the heart and kidney, with CKD-related endothelial dysfunction also involving TLR4/NF-κB." (PMID 41325840, 2025). "Given that milk EVs remain stable in circulation and exert anti-inflammatory effects through TLR4 inhibition, it is plausible that they may also confer protective effects against endothelial dysfunction, a key contributor to cardiovascular diseases." (PMID 41010478, 2025). "Activation of the TLR2 and TLR4 pathways by dentilisin leads to the upregulation of MyD88-dependent signaling, which triggers pro-inflammatory cytokines and excessive endothelial cell activation, contributing to endothelial dysfunction and CVD pathogenesis." (PMID 40136726, 2025). "Additionally, the damage-associated molecule patterns (DAMS) activate Toll-like receptor 4 (TLR4), amplifying inflammation, oxidative stress, cellular damage, and endothelial dysfunction." (PMID 39195453, 2024). "Specifically, visfatin/eNAMPT is an adipocytokine that has been proposed as a marker of endothelial dysfunction and vascular damage, and visfatin/eNAMPT was shown to produce in vivo endothelial dysfunction in mice via toll-like receptor-4 (TLR4)-mediated pathway." (PMID 38074158, 2023). "Additionally, the activation of TLR4 has been reported to induce oxidative stress and endothelial dysfunction." (PMID 33803842, 2021). "However, oxidative stress has also been linked with endothelial dysfunction in CNIT, with a recent paper highlighting the role of TLR4 signaling and induction of vascular inflammation (TLR4 gene up-regulated in our data)." (PMID 34063776, 2021). "These inhibitory effects of DOX on the TLR4/LPS-signaling pathway, including the reduction of the pro-inflammatory cytokines IL-1β and IL-6, could explain the improvement of endothelial dysfunction and diminishing of blood pressure." (PMID 34578849, 2021). "Moreover, Pearson’s correlation coefficient revealed that endothelial dysfunction significantly correlated with aortic expression of inflammatory markers, TLR-4, TNF-α and IL-1β." (PMID 25826421, 2015). "Additionally, by inducing oxidative stress, TLR4 leads to the endothelial dysfunction that is characteristic of this pathology." (PMID 25093580, 2014).